GSTP1 (glutathione S-transferase pi 1)
Diseases named in the same sentence as GSTP1 in open-access papers (continued):
Sharing a sentence is not in itself a finding about the gene and the disease.
tumor (continued). "Overall, we found that patients with the GSTP1 rs1695 AA genotype had a lower risk of tumor recurrence when treated with epirubicin, but not with MMC ((AG+GG)/AA: HR = 3.47, 95% CI = 1.75–6.89)." (PMID 26354850, 2015). "GSTP1 was found to be involved in the drug resistance, and inhibition of GSTP1 expression could reverse the drug resistance and induce tumour cell apoptosis." (PMID 25317080, 2014). "Notably, the concurrent methylation of CDH1, GSTP1 and a few other genes were found to be significantly associated with levels of AFP, recurrence free survival (RFS) and tumor numbers." (PMID 24635883, 2014). "Another study analyzed whole blood samples from 76 CRPC patients, treated by maximum androgen blockage, in order to detect circulating tumor cells (CTCs) and methylated DNA (using qMSP) for a five-gene candidate marker panel (GSTP1, APC, PTGS2, MDR1 and RASSF1A)." (PMID 25238417, 2014). "If these results are translated to TCC setting, it may be speculated that GSTP1 Ile/Ile would imply a higher antioxidant potential providing the favorable environment for tumor progression and worse prognosis." (PMID 24040330, 2013). "Further preclinical studies have shown that tumor sensitivity to TLK286 positively correlates with GSTP1-1 expression both in cell cultures and in human tumor xenograft models, and that treatment with therapeutic doses of the drug produces only mild bone marrow toxicity in mice." (PMID 24300447, 2013). "Specifically, high levels of GSTP1 in tumor cells may greatly limit the efficacy of antitumor chemotherapy." (PMID 24202339, 2013). "The results suggest that GSTP1 methylation is a major event in breast carcinogenesis and may act as a tumor-specific biomarker." (PMID 23226781, 2012). "Since GSTP1 is overexpressed in tumor cells and might be involved in anticancer drug resistance, 15d-PGJ2 binding to GSTP1 could lead to the development of irreversible inhibitors in anticancer therapy." (PMID 23094162, 2012). "If inactivated, GSTP1 may act as a caretaker gene leading to additional somatic genome alterations that promote tumor growth." (PMID 23226781, 2012). "In certain cases, the presence of GSTP1 expression despite GSTP1 methylation may be attributed to a heterogeneous cell population in the tumor." (PMID 23226781, 2012). "GSTP1-AA has been related with a higher enzymatic capacity for the conjugation of various cytotoxic drugs and a subsequent decrease of the cytotoxic effect of chemotherapy on tumour cells." (PMID 20216541, 2010). "As to GSTP1 and PON1 192 polymorphisms, the mutant Val and R alleles, respectively, were associated with a decreased risk of developing BC, while polymorphisms in PON1 55 and GLO1 were associated with an increased risk of this neoplasia." (PMID 19379515, 2009). "Several tumour types have also shown aberrant methylation at the CpG island in other genes, including the FAP-associated gene APC, detoxifying gene GSTP1, DNA repair gene MGMT, the potential metastasis inhibitor gene DAP-kinase, and Rb interact gene RIZ1." (PMID 17968429, 2007). "However the presence of GSTP1 HM in the corresponding tumor biopsies prior to hormonal therapy argues strongly against this assumption." (PMID 16803634, 2006). "Furthermore, as a molecular biomarker, GSTP1 methylation could be used in conjunction with other prognostic indicators, such as tumor stage, to improve the accuracy of predicting patient outcomes and guide therapeutic decisions." (PMID 40051701, 2025). "Cell division control protein 42 homolog (CDC42), GSTP1, and peptidyl-prolyl cis-trans isomerase A (PPIA) were associated with regulation of the stress-activated mitogen activated protein kinase (MAPK) cascade, which were closely related to the tumor cell proliferation." (PMID 37124724, 2023). "Therefore, exploring the interaction of GSTP1 and ferroptosis in tumor radioresistance may provide us with a new approach to tumor radiosensitization." (PMID 36589232, 2022).
tumor (continued). "However, recent research shows that GSTP1 is closely related to tumor occurrence and prognosis." (PMID 34238333, 2021). "While our data does not preclude toxicity arising from DNA damage, given the dynamic roles of GAPDH and GSTP1 in the hypoxic tumour microenvironment, such an effect of N3-AZA on their activities may partially explain the observed hypoxic cytotoxicity of the drug." (PMID 33640700, 2021). "Thus, it is tempting to speculate that, at least some of the genes detected here (e.g., RASSF1 and GSTP1) could be constitutionally methylated and, in such cases, methylated tumor cells may have originated from the constitutionally methylated normal cells." (PMID 32859265, 2020). "Thus, thiazolides may represent an interesting novel class of anti-tumor agents by specifically targeting tumor resistance mechanisms, such as GSTP1-1." (PMID 26043078, 2015). "In addition to enhancement of tumor progression, upregulated GSTP1 expression in TCC might also limit the efficacy of chemotherapeutic agents that act by inducing apoptosis via the JNK pathway." (PMID 21637416, 2010). "However, the finding of elevated GSTP1 expression within mucin-producing tumours suggests that diminished clinical response may be expected from oxaliplatin-treated tumours." (PMID 15655543, 2005). "In the in vivo experiments, a xenografted tumor model was constructed, and the expression of SPAG6 and GSTP1 in tumor tissues was detected by IHC." (PMID 39508041, 2024). "In patients with localized disease, pre-operative circulating methylated GSTP1 in plasma has been demonstrated to predict PSA recurrence and tumor aggressiveness." (PMID 38339274, 2024). "The methylation of the promoter region of GSTP1 and RASSF1A represents not only a common feature of tumor cells that escape in situ, but also a plastic change of tumor cells to adapt to the new environment after colonization." (PMID 37190171, 2023). "FLNA, GAPDH, glutathione S-transferase P1 (GSTP1), and galectin-1 (LGALS1) were related to the I-kappaB kinase/NF-kappaB signaling pathway, which was closely related to the apoptosis process of tumor cells." (PMID 37124724, 2023). "GSTP1 may participate in the regulation of cellular redox state by catalyzing the reaction of glutathione with intracellular reactive oxygen species and other electrophiles, thereby improving the antioxidant capacity of tumor cells and helping tumor cells to resist external killing factors." (PMID 36589232, 2022). "ACSL3, EPAS1, FASN, GSTP1, LDHB, and NEDD4L were identified as the candidate genes through the intersection of tumor-related genes, DEGs, and ferroptosis-related genes." (PMID 35223835, 2022). "In tumor samples from HCC patients, DNA methylation levels at repetitive elements and genes including GSTP1, RASSF1A, and p16 have been correlated with biomarkers of AFB1 exposure." (PMID 33445757, 2021). "In the present study, 2 new OBBPA-ddPCR assays were developed to increase sensitivity of tumour-specific detection of methylated RASSF1A and GSTP1 DNA fragments in serum samples of PCa patients." (PMID 34503269, 2021). "To determine the role of GSTP1 in the tumor-suppressive effect of PCSK9, we detected GSTP1 protein expression and JNK signaling activity." (PMID 33893729, 2021). "Some identified genes, such GSTP1, RARB, and RASSF1, which were previously suggested as methylation biomarkers for PCa, showed DMRs in tumor tissues." (PMID 35053153, 2021). "To validate this finding, we pretreated the tumor cells with 25 μM of ezatiostat (EZA), a known inhibitor of glutathione s-transferase 1 (GSTP1) followed by cold plasma treatment." (PMID 31931281, 2020). "TUNEL assay indicated extensive apoptosis in tumor tissues, suggesting that depletion of either NQO1 or GSTP1 triggers apoptosis, with the combined knockdown producing more extensive apoptotic cell death than the other groups." (PMID 33087132, 2020).
tumor (continued). "On the contrary, the combination treatment up‐regulated expression of several known tumour suppressor genes like CST6, TFPI2, GSTP1 and several others." (PMID 32720467, 2020). "The tumor volume was monitored every ten days using FUJIFILM Vevo3100 ultrasound imaging system and was compared among the control and the GSTP1 knockdown groups." (PMID 32526885, 2020). "Consistent with our in vitro finding, Gstp1 regulates LLC-SD tumor sensitivity to cisplatin, measured by visual examination of tumor size, tumor growth rate (Figure 2Eii) and tumor weight (Figure 2Eiii)." (PMID 31263672, 2019). "In the first phase, we used gene chip data obtained from the Gene Expression Omnibus (GEO, GSE14520-GPL3921) and The Cancer Genome Atlas (TCGA) to analyze GSTP1 mRNA expression in HCC tissues and matched para-tumor tissues." (PMID 29507666, 2018). "Univariate analysis showed that GSTP1 expression, as well as AFP, tumor number, tumor size, PVTT, TNM stage, and Edmondson-Steiner grade were related to OS and DFS in HCC patients." (PMID 29507666, 2018). "We have previously discovered and/or characterized tumor-specific DNA methylation of six genes (APC, GSTP1, HOXD3, KLK10, TBX15, and TGFβ2) in radical prostatectomy tumor samples." (PMID 30470249, 2018). "We found GSTP1 and GSTM3 among the proteins that consistently increased their levels during tumor growth." (PMID 29774096, 2018). "We performed analyses on CC tumor proteome dynamics and identified GSTM3 and GSTP1 as novel potential therapeutic targets." (PMID 29774096, 2018). "Gene chip analysis showed that the levels of GSTP1 and seven other GSTs were lower in HCC tissues than adjacent non-tumor liver tissues." (PMID 29507666, 2018). "Here we demonstrated that the inhibition of GSTM3 or GSTP1 activates JNK and p38 signaling leading cells to apoptosis and therefore decreasing the tumor volume." (PMID 29774096, 2018). "High GSTP1 expression was correlated with OS and DFS in the AFP concentration ≤ 400 ng/ml, single tumor number, tumor diameter > 3cm, and PVTT-present subgroups." (PMID 29507666, 2018). "The current analyses comprising all eligible articles revealed that promoter methylation of the p16, CDH1, RUNX3, MLH1, RASSF1A, p15, APC, GSTP1, Reprimo, and MGMT was significantly higher in blood samples of patients with GC compared with non-tumor controls." (PMID 29100425, 2017). "Multiple tumor-related genes are found to be commonly methylated in tissue samples in GC, such as p16, CDH1, RUNX3, MLH1, RASSF1A, p15, APC, DAPK, GSTP1, Reprimo, and MGMT etc.." (PMID 29100425, 2017). "Subgroup meta-analysis by geographical populations was performed for p16, RASSF1A, GSTP1, APC, RUNX3, SOCS1 and PRDM2 between HCC tumor tissues and adjacent tissues." (PMID 27835605, 2016). "It has been reported that GSTP1 is capable of inhibiting tumor growth by its interaction with the c-Jun N-terminal kinase (JNK1) signaling, suggesting its role as a tumor suppressor gene." (PMID 26585467, 2015). "In tumor-adjacent and tumor-distant tissues, the RASSF1A promoter was as frequently and the HIN-1, MGMT and GSTP1 promoters were almost as frequently methylated as in tumors." (PMID 26370119, 2015). "In fact, in early single-gene analysis, tumor suppressor genes including P16, CDH1 and GSTP1 were found to be hypermethylated in HCC." (PMID 25093504, 2014). "Two of these, GSTP1 and SPINT2 were previously reported tumor suppressor genes which were hypermethylated in tumors with corresponding down-regulated gene expression, while the other 2 (CYB5R2 and SH3YL1) represent potential novel tumor suppressor genes." (PMID 25093504, 2014). "Of the 16 tumor-normal pairs with presumed hypermethylated promoter loci in HCC (in genes BMP4, RASSF1,GSTP1, and TACSTD2), 5, 6, 14 and 16 of the 16 HCCs had decreased expression of the gene, respectively." (PMID 23437062, 2013).
tumor (continued). "What’s more, there are evidences to believe that GSTP1 methylation could trigger “epigenetic catastrophe” which involves hypermethylation of associated genes including APC (a tumor suppression gene), and RAR-beta (tumor suppressor gene involved in cell cycle and apoptosis)." (PMID 24086370, 2013). "Five hypermethylated loci harbored by four genes (GSTP1, TACSTD2, BMP4 and RASSF1) and three hypomethylated loci in three genes (ARHGAP8, GPR35 and DLGAP1) were validated using 7 assays with 12 tumor-normal tissue pairs from this study." (PMID 23437062, 2013). "In our study group, 37.5%, 61.60%, 58.92% and 20.53% of the ESCC tumours had p16, DAPK, GSTP1 and BRCA1 promoter methylation respectively, which was significantly higher than adjacent normal tissues." (PMID 23596512, 2013). "Statistical analysis revealed 3 genes (HIC1, GSTP1, and RASSF1) capable of significantly predicting tumor recurrence." (PMID 24252461, 2013). "In conclusion, the present study showed aberrant tumor-specific methylation alterations for APC, BIN1, BMP6, BRCA1, CST6, ESR-b, GSTP1, P14, P16, P21, PTEN and TIMP3 in the studied cohort." (PMID 22695536, 2012). "The eight genes displaying variable DNA methylation patterns in a significant number of tumours (ABCB1, BRCA1, CDKN2A, FOXC1, GSTP1, IGF2, PPP2R2B and PTEN) within the discovery cohort were tested for association with survival by a logrank test." (PMID 20338046, 2010). "The identified genes are involved in drug transport and detoxification (ABCB1, DNAJC15, GSTP1, RAB6C), DNA damage repair (BRCA1) as well as tumor cell proliferation/invasion (APC, CDH1, ESR1, HIC, PLAU, RASSF1, SULF2, TGM2)." (PMID 20544021, 2010). "Classical tumour suppressor genes and genes involved in chemosensitivity, such as hMLH1, p16, p15, Rb, VHL, E-cadherin, GSTP1, and BRCA1, or the DNA repair gene MGMT, undergo epigenetic inactivation by hypermethylation of their regulatory regions." (PMID 19144202, 2009). "For RASSF1A, CCND2, GSTP1, TWIST, and APC genes, the proportion of methylated genes was significantly higher in the ER-positive than in the ER-negative tumor group." (PMID 18485221, 2008). "In all 49 tumours and 6/7 HGPIN that showed IGFBP3 methylation, methylation of GSTP1 was also detected." (PMID 17453001, 2007). "Methylation of IGFBP3 was only detected in those samples (both tumour and the majority of HGPIN) that demonstrated GSTP1 methylation." (PMID 17453001, 2007). "Promoter hypermethylation in 10 tumour-related genes (APC, E-cadherin, GSTP1, hMLH1, MGMT, p15, p16, SOCS1, TIMP3 and TGF-beta RII) was determined by quantitative methylation-specific PCR (MethyLight)." (PMID 15942635, 2005). "In a CART analysis, optimal separation between tumour and normal tissues was achieved using RARB2 plus GSTP1 hypermethylation." (PMID 15292941, 2004). "Only five resistance proteins (MDR1, TYMS, GSTP1, MGMT, MVP/LRP) were increased in comparison to sensitive tumours, while the other resistance factors revealed only marginal changes." (PMID 12177790, 2002). "Based on the prior literature on related tumor types, we hypothesized that two additional potential markers may be of use: stratifin (SFN) and glutathione S-transferase Pi (GSTP1)." (PMID 40004538, 2025). "Furthermore, gene coexpression analysis was conducted to explore the relationships between GSTP1 and LPCAT1 expression and the tumor microenvironment (TME) and between GSTP1 and 33 immune-related genes in tumors in the TCGA database." (PMID 40555906, 2025). "Additionally, assessing GSTP1 methylation could provide prognostic information, as some studies have suggested a correlation between hypermethylation and poor clinical outcomes, including advanced tumor stage, higher recurrence rates, and reduced overall survival." (PMID 40051701, 2025). "IHC was used to determine the expression of GSTP1 and SPAG6 in tumor tissues." (PMID 39508041, 2024).
tumor (continued). "Another piece of evidence is that both GSTP1 and RASSF1A show high DNA methylation in circulating tumor cells or paired plasma-derived exosomes of mCRPC and some genes related to androgen synthesis are also hypermethylated (such as CYP11A1, CYP11B1, CYP17A1 and CYP19A1)." (PMID 37190171, 2023). "PCSK9 inhibited HCC cell proliferation, cell cycle progression, and apoptosis by interacting with GSTP1 and suppressing JNK signaling, suggesting that PCSK9 might act as a tumor suppressor and be a therapeutic target in HCC patients." (PMID 33893729, 2021). "This phenomenon may constitute an underexplored mechanism of chemoresistance in tumor cells under EMT, implying that expression of the genes DPYD, TYMS, MTHFR, ERCC1, ERCC2, XRCC1, and GSTP1 may be modulated EMT-TFs." (PMID 33429840, 2021). "In contrast, GSTP1 expression showed high expression in the peripheral part of the tumor compared with the non-involved part." (PMID 34563043, 2021). "At first, we noticed gradual increase in the GSTP1 protein across tumor grades, although without significant difference." (PMID 33953831, 2021). "We found, both in cases and controls, that neither the age at prostate biopsy nor the time interval between two negative biopsies were associated with methylation of GSTP1, APC, C1orf114, GABRE, PITX2, or LINE-1 in non-tumor prostate tissue." (PMID 31666119, 2019). "High GSTP1 was correlated with low serum AFP (P = 0.003) and small tumor size (P = 0.013)." (PMID 29507666, 2018). "Sixteen primary matched tumor and serum were analyzed by quantitative methylation specific PCR (QMSP) to determine analytical and clinical sensitivity of the genes tested (SSBP2, MCAM, ERα, ERβ, APC, CCND2, MGMT, GSTP1, p16 and RARβ2)." (PMID 28147335, 2017). "For the remaining genes (SSBP2, MCAM, ERα, ERβ, CCND2, MGMT, GSTP1 and p16) methylation in serum DNA was always corresponding to methylation of tumor DNA, while methylation of tumor DNA was not always corresponding to methylation of serum DNA." (PMID 28147335, 2017). "In conclusion, although GSTP1 does not seem to be useful for histological evaluation of core biopsies, as previously demonstrated, its behavior in the various stages of tumor development is interesting and should be better investigated." (PMID 27594734, 2016). "Our present investigation had covered a broad group of tumor-related pathway genes, including p16 (cell-cycle control), DAPK, RASSF1 (apoptosis), BRCA1, MLH1 (DNA repair), ECAD (cell-cell adhesion), GSTP1 (carcinogen metabolism), MINT1, MINT2 and MINT31 (methylated loci in tumors)." (PMID 26098903, 2015). "If GSTP1 methylation is not altered, DNA methylation was probably not involved in tumor development and epigenetic drugs are unlikely to be effective." (PMID 26086362, 2015). "In contrast, in only one of the tumor-adjacent tissues and none of the tumor-distant tissues, the methylation status of the GSTP1 promoter was ≥ LOQ." (PMID 26370119, 2015). "Positive GSTP1 was only found in 5 tumors, and the other 63 samples were completely negative for GSTP1 in the epithelial tumor cells." (PMID 26086362, 2015). "Intriguingly, GSTP1 immunostainings revealed that ~ 90% of the tumors from the PCa2 cohort did not express GSTP1 in any of the epithelial tumor cells." (PMID 26086362, 2015). "The five tumors that stained positively for GSTP1 showed a mixed population of positive and negative tumor cells, clearly demonstrating intra-tumor heterogeneity at the GSTP1 level." (PMID 26086362, 2015). "There was a trend for the absence of methylation at ABCB1, FOXC1, PPP2R2B, and GSTP1 in both the basal-like and normal-like tumours, while IGF2, MLH1 and PTEN were hypomethylated in the basal-like tumours but not in the normal-like tumours." (PMID 20338046, 2010).